CD44 (CD44 molecule (IN blood group))
Diseases named in the same sentence as CD44 in open-access papers (continued):
Sharing a sentence is not in itself a finding about the gene and the disease.
tumor (continued). "CD44-IR700-mediated PIT also decreased CD31 expression levels indicating significant destruction of vasculature that may have also contributed to the profound decrease of tumor growth and catastrophic cell death in the CD44 positive treated tumors." (PMID 27302409, 2016). "The frequency of tumour specific memory CD8+CD122+CD44+ T cells was significantly higher in mice vaccinated with the sustained release vaccine in peripheral lymphoid sites sampled consistent with our previous data prior to tumour challenge." (PMID 27756214, 2016). "The expression of CD133 and CD44 in tumor and peritumoral tissues was detected by IHC." (PMID 27329727, 2016). "Intriguingly, the number of CSCs (CD133+/CD44+) was enhanced with increasing tumor grade." (PMID 27172799, 2016). "The most studied molecules in tumour cell adhesion are integrin α2β1, CD44 s and MUC16." (PMID 27074785, 2016). "However, CD44 was less often found in the tumor epithelium in advanced-stage tumors, though one-third of the tumors expressed CD44 in the epithelium." (PMID 27590006, 2016). "In fact, according to our in vivo results, the CD133+/CD90+/CD44+ tumor stem cells may be responsible for dissemination of glioblastoma, which leads to reduced patient survival." (PMID 27244897, 2016). "Also, a causal role of Notch-Jagged signalling in mediating tumour-initiation potential and/ or drug resistance of the CD24+ CD44+ hybrid E/M cells remains to be directly tested." (PMID 27170649, 2016). "Having established that CD24 specifically affects cisplatin sensitivity of these HNSCC lines and arguably has no bearing on their early radiation sensitivity profile, we intended to study the expression pattern of CD24 and compare it with the prominent CSC marker CD44 in HNSCC tumor sections." (PMID 27276062, 2016). "Since almost all NB4 cells highly express CD44, tumor cells were identified by CD44 expression." (PMID 27329592, 2016). "Future studies using normal and tumor keratinocytes from the same subject may provide even more reliable information about the regulation of CD44 expression by extracellular agents." (PMID 27505250, 2016). "The results suggest CD44+/CD49f+ may be a good marker for both basal mammary stem cells and basal tumor‐initiating cells as MCF10F and trMCF present a significant fraction of double‐positive cells whereas both of them are not tumorigenic." (PMID 26775583, 2016). "CD44 was recently identified as a novel marker for vasculogenic tumor cells; the reduction of CD44 expression suppressed vascular formation and targeting CD44 attenuated tumor angiogenesis." (PMID 27302409, 2016). "Moreover, NHKs treated with FCS, in the presence of calcium, showed similar expression of CD44 transcripts as several tumor cells." (PMID 27505250, 2016). "CD44 was mainly associated with the cell surface and tended to stain cells in the outer layers of the tumor islands formed by the UT-SCC-14 cells; no staining was observed in the stroma." (PMID 26880935, 2016). "However, in the identified studies, CD44 expression was highly correlated with tumor TNM classification (OR 2.38, 95 % CI 1.23–4.60; P = 0.01) and decreased overall survival (RR 1.49, 95 % CI, 1.26–1.76; P < 0.00001)." (PMID 27330410, 2016). "Cells that migrated out of the tumor spheres gradually lost the expression of CD44 and CD24." (PMID 27521216, 2016). "Furthermore, TAM-derived IL-6 induced CD44+ stemlike cell expansion by activating STAT3, and blocking IL-6 with tocilizumab ablated CD44+ sphere formation in vitro and tumor growth in patient-derived HCC xenografts." (PMID 26980947, 2016). "However, there was a significant correlation, with disease-specific survival (DSS), in that patients with CD44 low expression patterns tumours have longer survival outcome (p <0.03)." (PMID 27454254, 2016). "Interestingly, changes in the CD44/ALDH ratio of tumor spheres compared to tumor cells growing under adherent conditions were observed." (PMID 26742076, 2016).
tumor (continued). "Tumor and non-tumor samples differed significantly in the expression of 10/22 genes: CCNB1, CLDN4, CLDN6, MMP2, MUC1 (all: p < 0.05), BAG1, SERPINB3 (all: p < 0.01), CD44 (standard variant), MKI67, and MYBL2 (all: p < 0.001)." (PMID 27542596, 2016). "In a larger series, CD44 was present in about half of the tumours and indicated a good prognosis." (PMID 27590006, 2016). "The use of a CD44-targeting peptide, Ac-KPSSPPEE-NH2, is another therapeutic strategy, documented by Finlayson, to combat CD44-associated pathological activities in experimental vascularized eye, tumor xenografts, or in clinical trials." (PMID 26904028, 2016). "Similarly to CD44+/hi phenotypes, sorted FGFR+/hi cells had larger volumes, formed more tumor spheres, grew faster in vivo with bigger tumor mass, and expressed more CD44, EpCAM, and HER2." (PMID 27107424, 2016). "On the other hand, since RG7356 is not mouse cross-reactive, the secretion of murine cytokines cannot be initiated by direct binding of RG7356 to CD44 on immune cells but can be either FcγR-mediated and/or indirectly triggered by tumor-derived immune modulators." (PMID 27463372, 2016). "Therefore, it is reasonable that CD74 knockdown suppresses CSC via CD44, resulting in tumor growth inhibition in the xenograft model." (PMID 27626171, 2016). "The CD133 and CD44 markers were used to ascertain CSCs in most tumor tissues." (PMID 27564296, 2016). "ALDH1 positivity was thus associated with a BRCA1 defect and we additionally find this association to be independent of tumor sub-type unlike the CD44/24 profile." (PMID 27229859, 2016). "Notably, in TCC specimens, nuclear β-catenin was expressed more restrictedly in the CD44+ tumor cell subpopulation, implying that the transcriptional activities of β-catenin play a key role in the maintenance of stemness." (PMID 27472396, 2016). "Indeed, this CD44+ population gave rise to thymic tumours when transplanted intravenously into recipient mice, again consistent with an origin in ETPs in this model system." (PMID 26753883, 2016). "We demonstrate that Spry4 knockdown MDA-MB-231 cells led to enhancement of CSC features, including increased CD133+CD44+ subpopulation and mammosphere formation, decreased sensitivity to Paclitaxel treatment in vitro, and increased capacity for xenograft tumor initiation in vivo." (PMID 26973433, 2016). "Additionally, higher expression levels of CD44 in tumor tissues are correlated with higher serum sCD44 levels, suggesting that at least a part of sCD44 found in HL patients originated from tumor cells." (PMID 27563824, 2016). "An increased proportion of CD24+ and CD44+ cells in PDAC cell lines compared with the original tumor tissues might indicate that these cells had a selective advantage in cell culture." (PMID 27414409, 2016). "CD44 is a hyaluronic acid receptor that is involved in tumor development." (PMID 27563824, 2016). "Moreover, selective proteasome inhibition enabled mammary epithelial cells to acquire certain morphologic and functional characteristics reminiscent of cancer stem cells, including CD44 expression, self-renewal, and tumor formation." (PMID 26930717, 2016). "In accordance with this hypothesis, cell fractions of unmodified FGFR2+ or CD44+ cell grew faster, formed more tumor spheres in vitro, and established faster growing and larger tumors in vivo." (PMID 27107424, 2016). "Although—theoretically—blocking the CD44 ligand hyaluronan might prevent peritoneal dissemination, its therapeutic value is controversial: both tumour promoting and tumour repressing effects were reported after blocking CD44 intraperitoneally with hyaluronan." (PMID 27074785, 2016). "Similarly, following the inoculation of pure mCherry-expressing CD44+/CD24low/− cells to mice, the tumors consisted of 52 ± 6.9% mCherry-expressing cells but only 4.5 ± 1.1% of the mCherry-expressing tumor cells retained the CD44+/CD24low/− phenotype." (PMID 27835603, 2016).
tumor (continued). "Low-molecular weight hyaluronan induces the formation of a complex containing CD44, TLR2/TLR4, the actin filament-associated protein AFAP-110, and a myeloid differentiation factor MyD88, which triggers cytoskeleton activation and results in tumor invasion." (PMID 26869928, 2016). "In a subset of PC tumor samples selected based on large difference in expression level on the mRNA level, we analyzed the protein expression of CD44, CD44v6, and VEGF by immunohistochemistry (based on established in-house methods and availability of antibodies)." (PMID 27542596, 2016). "Cytoplasmic and membranous CD74 was also detected in MSTO tumor cells as well as CD44." (PMID 26883190, 2016). "Since there was a partial quenching in the fluorescence of IR680 in the sections, which may affect the measurements of tumour dimensions, we stained the live sections with CD44-PE and TM1-FITC." (PMID 27827443, 2016). "Furthermore, CD44, a marker for cells with tumor initiating potential, was identified as a BTNBC marker in both PDX (log2FC = 2.14, FDR = 5.91E–04) and cell line (log2FC = 2.58, p = 8.66E–03) but not in clinical (log2FC = 0.06, FDR = 0.79) datasets." (PMID 26980748, 2016). "Consequently, CD44 cannot be considered as handy tool to establish the tumor behavior, prognosis and 5- year survival rate of these tumors." (PMID 28008391, 2016). "CD44 expression in fibroblasts was confined to the areas surrounding the tumors but was also highly upregulated in the hyperplastic epidermal regions of the tumor itself." (PMID 26771241, 2016). "Pharmacological blockade of A3AR generated a chemosensitizing effect, enhancing the effectiveness of the MRP1 transporter substrate, vincristine, reducing tumour size and the levels of CD44 and Nestin stem cell markers as well as the Ki-67 proliferation indicator." (PMID 27634913, 2016). "Cell apoptosis plays an important role in tumor cell growth; thus, we further assessed whether CD44-PEG-GNCs combined with NIR laser radiation and X-ray radiation can induce more apoptosis." (PMID 27255899, 2016). "CD44, one of the members of cell adhesion molecules, control cell behavior by mediating contact between cells and the extracellular matrix and are therefore involved in pathological conditions including tumor progression and metastasis." (PMID 27809879, 2016). "In addition to the co-expression of CD133 and CD44 in clinical tumor samples, the co-expression of CD133 and CD44 was also observed in the tumor samples from the PDX models." (PMID 27329727, 2016). "Furthermore, CD44 expresses various isoforms in different types of tumor and exhibits different stem-cell behaviors." (PMID 25993512, 2015). "Moreover, the same datasets revealed high mRNA expression of the c-Met co-receptor CD44 in all MB tumor samples." (PMID 25625039, 2015). "Importantly, CD44, which we found to be overexpressed in vasculogenic tumor cells, has been well described in relation to both epithelial-to-mesenchymal transition and tumor-initiating stem cells." (PMID 26189059, 2015). "In addition, CD44–HA binding can activate the ankyrin-based cytoskeleton and various Rho GTPase signalling pathways during tumour progression." (PMID 26287771, 2015). "We conclude that elevated CD44 expression on tumour cells within the systemic circulation increases the efficiency of post-intravasation events and distant metastasis in vivo, consistent with its association with increased distant recurrence and reduced disease-free survival in patients." (PMID 25888636, 2015). "Furthermore, peptide inhibition of CD44–HA binding significantly reduced seeding and tumor growth of intravenously introduced B16-F10 melanoma cells in lungs in a model of metastasis." (PMID 26029216, 2015).
tumor (continued). "This supports the concept that targeting CD44 may render tumor cells more sensitive to therapeutic agents." (PMID 25870596, 2015). "We further analyzed the excised tumor for series of CSC markers (CD44, CD24 and ABCG2)." (PMID 26176230, 2015). "For example, treatment of rats with a hyaluronan containing barrier along with colorectal cell lines expressing different amounts of the CD44 cell surface marker, a ligand for hyaluronan, increased the tumor nodule count in vivo within the peritoneal cavity and tumor proliferation in vitro." (PMID 25785270, 2015). "CD44 interacts with osteopontin and regulates its cellular functions leading to tumor progression." (PMID 26464794, 2015). "For long, the role of CD44 in tumor progression and metastasis remained unclear." (PMID 25904917, 2015). "Our findings offer new opportunities for future treatment strategies, as targeting CD44 may not only affect VM, but may also inhibit tumor angiogenesis and target the cancer stem cell population." (PMID 26189059, 2015). "Tumors associated with high CD44 expression are known to be more invasive, therefore it is not surprising that it is more difficult to target these tumor cells by radiotherapy." (PMID 25749043, 2015). "The results of the performed studies are consistent with the hypothesis put forward by Herrlich and colleagues, stating that CD44 might play a dual role in cancer pathogenesis, acting as either an oncogene or a tumour-suppressing factor." (PMID 25999819, 2015). "Indeed, isolated CD44+/CD24−/lowLin− CSCs express a five-fold increase in BMI1 compared to tumour cells also derived from the same human breast carcinoma-derived xenograft tumour, but lacking CSC marker expression." (PMID 26270676, 2015). "Inhibiting cleavage of CD44 inhibits tumor cell migration on a HA substrate, suggesting that CD44 cleavage could release cells bound to a HA ECM." (PMID 25999946, 2015). "Immunohistological and western blot analysis of the tumour tissue revealed a significant upregulation of CD44, phosphorylated Hck, as well as activated Src (via ablation of the inactivating residue at Y527) in the day 9 tumours from animals treated with DTX as compared with vehicle-treated controls." (PMID 25669750, 2015). "In multiple papers, it has been suggested that exposure to IL-21 alone causes lymphocytes to remain in or differentiate into a minimally differentiated phenotype (CD62L+CD44−), and that these lymphocytes have greater anti-tumor capacity relative to cells expanded in other gamma chain cytokines." (PMID 25903148, 2015). "In the present study, licofelone significantly suppressed increases in DclK1 along with other CSC markers (Lgr5, CD133 and CD44) in correlation with its inhibition of tumor progression, suggesting that licofelone may kill CSCs." (PMID 25906749, 2015). "The fact that both CD44 and HA are overexpressed at tumor attachment sites and that HA binding to CD44 stimulates a variety of tumor cell-specific functions and tumor progression suggests that the HA-CD44 interaction is a critical requirement for tumor progression." (PMID 26448762, 2015). "Interestingly, the CD44+α2β1+ Du145 cell population was only slightly enriched in tumor-initiating cells and its tumor-initiating capacity was actually lower than in CD44+ Du145 cells (TIF 1/9, 152 vs. TIF 1/530, P = 1.27e-07)." (PMID 26246472, 2015). "In addition, these CD44+ relapsing cells have the capacity to proliferate, suggesting that these cells generate a relapsing tumor, with a more differentiated phenotype." (PMID 25797268, 2015).
tumor (continued). "Both WT and Gpa33−/− mice exhibited activation of the WNT pathway, shown by elevated β-catenin protein and upregulated expression of the WNT target genes, CD44 and Lgr5, in tumours compared to normal epithelium, consistent with CTNNB (encoding β-catenin) being a known AOM target." (PMID 26035389, 2015). "We also confirmed the direct interaction between TrkA and CD44 in tumor xenografts using a PLA." (PMID 25840418, 2015). "The number of tumor spheroid formations of cancer stem like CD44+/CD24- cells delivered from MDA-MB-231 cells was significantly reduced after carbon ion beam compared to X-ray irradiation, and it was extremely decreased when the carbon ion beam combined with CDDP." (PMID 26338199, 2015). "Moreover, it suggests a function for CD44 as a gatekeeper of this newly adopted phenotype and a marker of increased tumor malignancy through tumor cell plasticity." (PMID 26189059, 2015). "In focusing on the later stages of the metastatic cascade, our study definitively shows that CD44 contributes to post-intravasation events of the metastatic cascade in vivo, where CD44 expression correlates with increased tumor burden at distant sites and reduces survival." (PMID 25888636, 2015). "Indeed, knockdown of CD44 resulted in reduced tumor cell migration and suppressed network formation in vitro." (PMID 26189059, 2015). "Moreover, implantation of the PEM inhibited tumor-stromal interaction-related expression of proteins such as CD44, SPARC, matrix metalloproteinase-2, and vimentin." (PMID 25983747, 2015). "In some PDX submitted to the anticancer treatment, almost all the tumor cells became CD44+." (PMID 26244163, 2015). "By comparing the zeta potential distributions of EVs after their immunochemical reaction with normal IgG, and the anti-human CD63 and anti-human CD44 (cancer stem cell marker) antibodies, EVs of tumor origin circulating in blood were differentially detected in the real sample." (PMID 25928805, 2015). "Moreover, the downregulated HOTAIR expression in CD117+CD44+ CSCs significantly decreased the tumor growth and lung metastasis in xenograft mice." (PMID 25792974, 2015). "Although the mechanism by which CD44 induces drug resistance and tumor recurrence is unknown, our findings indicate that this does not appear to be via MDR1-dependent mechanism." (PMID 25823654, 2015). "Newly designed therapeutic strategies could therefore involve the elimination of these CD44+ cells, which we have described as being responsible for tumor recurrence following anticancer treatment." (PMID 26244163, 2015). "CD44 and c-met are supposed to promote the development of tumor malignant behavior synergistically." (PMID 25658794, 2015). "Treatment with the anti-CD44 mAb significantly reduced tumor volume to the half (450 mm3 ± 6.2)." (PMID 25797268, 2015). "We used TUNEL apoptosis assay on tumor sections to test whether the tumor suppression with combination HA-PEI/HA-PEG/MDR1 siRNA CD44 targeted nanoparticle and paclitaxel treatment is related to induced apoptosis in treated tumor." (PMID 25687880, 2015). "In addition to the therapeutic uses of various anti-CD44 antibodies, a study has used an anti-CD44 antibody for tumor imaging." (PMID 25954275, 2015). "Furthermore, we also identified high CD44 expression in liver and diaphragm metastatic tumors comparing to the primary tumor of CWR22rv1 orthotopic xenografts." (PMID 25483103, 2015). "Furthermore, when the tumor tissues were dissociated into single-cell suspensions, the subpopulation of Epcamhigh/CD44+ were detected by Flow Cytometry." (PMID 26564738, 2015). "Noteworthily, the CD44+90+ cells have been regarded as tumor cell progenitors and might serve as cancer stem cells (CSCs)." (PMID 26000019, 2015). "Interaction of CD44 with growth factor receptors stimulates the proliferation and invasion of cancer cells; however, its interaction with ezrin/radixin/moesin proteins activates the tumor suppressor, merlin, to inhibit cancer growth." (PMID 26572077, 2015).